GPC6 (glypican 6)
Diseases named in the same sentence as GPC6 in open-access papers (continued):
Sharing a sentence is not in itself a finding about the gene and the disease.
tumor (continued). "Thus, it appeared that when the tumor expansion rate was high, overexpression of GPC6 altered the whole-FOV activity patterns qualitatively by favoring more frequent but smaller events, whereas when tumors expanded slowly, tumors with GPC6 had reduced overall calcium activity." (PMID 38802334, 2024). "Having established a differential influence of GPC6 on whole-FOV neuronal activity changes as a function of local cortical tumor expansion rate, we next asked whether ongoing calcium activity patterns in neuronal populations also depended on distance from tumor cells." (PMID 38802334, 2024). "Our results suggest that GPC6 may play a role in tumor metastatic progression." (PMID 31199813, 2019). "While GPC1 and GPC2 exhibited a strong net upregulation in tumor samples over normal across the board of cancer types, other members like GPC4, GPC5, and GPC6 were characterized by tissue-specific cancer expression patterns." (PMID 36944188, 2023). "Here we found high GPC6 expression in a cell line with HER2-negative status, which is an indicator that our results are valid and should not only be attributed to the tumor microenvironment." (PMID 33742285, 2021). "In particular, some of them are known to be up-regulated in tumor cells enhancing the aggressive nature of tumors (e.g. EFEMP1), promoting migration and invasion of cancer cells (e.g. GPC6) or acting as proto-oncogenes (e.g. MET)." (PMID 26918450, 2016). "The remaining 8 PGs, for which transcripts were expressed at a frequency of 84% (GPC1), 86% (GPC3), 88% (GPC4), 70% (GPC6), 100% (SDC1), 94% (SDC2), 93% (SDC3) and 95% (SDC4) of the tumour cases, respectively, were found to be differently modulated." (PMID 25935541, 2015). "Of note, in our model GPC6 expression was introduced into all tumor cells, whereas in the human samples GPC6 was likely not equally as homogeneously expressed throughout the tumor." (PMID 38802334, 2024). "Whereas these results from 3xCR tumor animals indicate that overall calcium events were progressively diminished at increasing distances from the tumor, in GPC6 animals there was no such difference in near/far ratios between slow and fast expansion periods." (PMID 38802334, 2024). "Unexpectedly, this result exposed a significant difference in somatic activity patterns inside vs. outside the tumor margin, with a strong dependence on tumor genotype, and with a drop-off with distance in GPC6 animals, not 3xCR." (PMID 38802334, 2024). "Next, we analyzed the spatiotemporal patterns of cortical tumor invasion, comparing the 3xCR tumor model with and without the overexpression of GPC6." (PMID 38802334, 2024). "Moreover, further significantly upregulated genes such as DOCK10, GPC6, and FSCN1 have been related to enhanced tumor cell migration and/or invasion." (PMID 35163822, 2022). "Moreover, the expressions of GPC-1, GPC-2, GPC-4, GPC-5, and GPC-6 were not significantly different between tumor and normal liver tissues." (PMID 33902495, 2021). "Indeed, several pro-proliferation proteins were uniquely identified in CM2D such as PICALM, which positively regulate cell proliferation and GPC6, MAPK1, ILK and MIF, all involved in cell proliferation, migration and invasion, including that of tumor cells, cardiomyocytes and endothelial cells." (PMID 34884877, 2021). "GPC6 tumors did not seem to influence calcium event strength in this distance-dependent manner, and under fast tumor expansion rates, all calcium metrics—except event rate, which did not depend on distance—were significantly less correlated with tumor distance than in 3xCR animals." (PMID 38802334, 2024). "The mean activity (ΔF/min) was 2.3-fold greater in 3xCR than in GPC6 brains during slow, but not fast, expansion (p = 0.008 and p = 0.15, respectively, WR test), indicating an unexpected shortage of overall synaptic and somatic activity in GPC6 mice during slow tumor expansion." (PMID 38802334, 2024).
tumor (continued). "Both CM presented proteins involved in proliferation of both tumor and non-tumor cells, of which CAPN1, CST1, LAMC2 and RANBP3 stood out in CM3D and GPC6, ILK, MAPK1, MIF and PICALM in CM2D." (PMID 34884877, 2021).
cancer (12 papers, 2015 to 2025). A tumor composed of atypical neoplastic, often pleomorphic cells that invade other tissues. "GPC6 has also been implicated in many cancers and other diseases." (PMID 31199813, 2019). "Pan-cancer analysis using ~9,500 RNA-seq samples from 32 different tumors also confirmed that genes with the highest correlation in expression levels with GPC6 across the 32 tumors were enriched with genes related to cell adhesion and migration." (PMID 31199813, 2019). "To determine a potential mechanism of GPC6 regulation during cancer progression, we hypothesized that GPC6 was targeted by miR-509-3p." (PMID 31199813, 2019). "We have demonstrated that PE5 kills cancer cells through apoptosis associated with the p21WAF1/CIP1 induction and JNK inactivation, thus a PE5 down-regulation of GPC6 might contribute to JNK inactivation." (PMID 26918450, 2016). "For many targets like CLMP, PDGFRB, NOTCH2, and GPC6, TCGA SARC samples had the highest median expression compared with other cancer types in the TCGA Pan-Cancer Atlas." (PMID 40814001, 2025). "A mesenchymal signature (VIM, FN1, LOX, GPC6, ZEB1) was defined as the highest co-correlated mesenchymal marker set in Cancer Cell Line Encyclopedia (CCLE) NSCLC cell lines." (PMID 31581742, 2019). "Here, a cancer-wide GPC expression study, using clinical cancer patient data in The Cancer Genome Atlas, reveals net upregulation of GPC1 and GPC2 in primary solid tumors, whereas GPC3, GPC5 and GPC6 display lowered expression pattern compared to normal tissues." (PMID 36944188, 2023). "Glypican proteoglycan (GPC1 and GPC6), core membrane-anchored heparan sulfate proteoglycans, were upregulated in ESCC tissues compared with para-carcinoma tissues, whereas syndecan proteoglycans (SDC1, SDC2, and SDC4), transmembrane heparan sulfate proteoglycans, were downregulated." (PMID 35840985, 2022). "Compared with GPC-1, GPC-2, GPC-3, and GPC-5, few studies have investigated the mechanism and prognostic significance of GPC-4 and GPC-6 expressions at the mRNA level in malignant tumors, and no related reports have been found in HCC." (PMID 33902495, 2021). "Our conclusions underscore the necessity to elucidate the molecular mechanism of GPC6 and TMEM132D involvement in T-cell infiltration and their impact on cancer progression and also highlight their possible importance as putative diagnostic/therapeutic targets." (PMID 26448945, 2015).
neurodegenerative disease (1 paper, 2025). A disorder of the central nervous system characterized by gradual and progressive loss of neural tissue and neurologic function. "GDE2 dysfunction, GDE2-dependent Wnt activation, and GPC6 have been independently implicated in neurodegenerative diseases with TDP-43 abnormalities." (PMID 41381859, 2025).
skeletal dysplasia (1 paper, 2025). Any Mendelian diseases that affects growth and development of the skeleton. "Mutations in GPC6 are associated with omodysplasia 1(OMOD1), a rare autosomal recessive skeletal dysplasia characterized by severe congenital micromelia (reduced head and trunk size and gross skeletal abnormalities) and shortening of the humerus and femur." (PMID 41376803, 2025). "Dysfunctional PGs such as GPC6 represent a functional link between IVDD and skeletal dysplasia." (PMID 41376803, 2025).
GPC6 also shares sentences with these, for which no sentence is quoted: lung carcinoma (5 papers); Alzheimer disease (2); cutaneous melanoma (2); gastric cancer (2); retinoblastoma (2); Stroke (2); 3-M syndrome (1); atherosclerosis (1); cervical cancer (1); coeliac disease (1); colorectal cancer (1); congestive heart failure (1); Crohn disease (1); diabetes (1); dysplasia (1); escherichia coli infection (1); hepatocellular carcinoma (1); hyperthyroidism thyrotoxicosis (1); infection (1); invasive breast carcinoma (1); malignant neoplasm of the thyroid gland (1); non-small cell lung carcinoma (1); Obesity (1); osteoarthritis (1); ovarian tumors (1); Parkinson disease (1); pouchitis (1); prostate carcinoma (1); sarcoma (1); triple-negative breast carcinoma (1).